STIM1 (stromal interaction molecule 1)
Diseases named in the same sentence as STIM1 in open-access papers (continued):
Sharing a sentence is not in itself a finding about the gene and the disease.
infection (12 papers, 2013 to 2024). The state of being infected such as from the introduction of a foreign agent such as serum, vaccine, antigenic substance or organism. "It suggests that increased Ca2+ levels in the ER are not related to Ca2+ store depletion but are related to the upregulated expression of STIM1 caused by vvIBDV infection." (PMID 35891504, 2022). "HeLa cells co-expressing YFP-CERT and mChSTIM1 were infected with a strain of C. trachomatis expressing CFP and the association of CERT and STIM1 with the inclusion was analyzed by confocal fluorescence microcopy 4 and 8 hours post infection." (PMID 25915399, 2015). "Moreover, CERT and STIM1 co-localized at the inclusion membrane as early as 4h post infection and remained associated throughout the development cycle." (PMID 25915399, 2015). "Therefore, STIM1 was used as an ideal target protein to explore whether the changes in serum Ca2+ levels were caused by vvIBDV infection." (PMID 35891504, 2022). "As anticipated, at 4 hours post infection, STIM1 and Orai1 were found to redistribute within their respective membranes and appear as “puncta”, indicating the formation of closed ER-PM CSs and the opening of SOCE channels in PRRSV-infected cells." (PMID 36972295, 2023). "In conclusion, we demonstrate that vvIBDV infection upregulates the expression of STIM1, and the elevated expression of STIM1 leads to increased Ca2+ levels in the ER, which facilitates vvIBDV replication." (PMID 35891504, 2022). "The results of iTRAQ showed that the expression level of STIM1 significantly increased after vvIBDV infection." (PMID 35891504, 2022). "To investigate the relationship between STIM1 expression level and vvIBDV infection, we used laser confocal microscopy for intuitive observation." (PMID 35891504, 2022). "Our previous study showed that EBV infection enhances STIM1 aggregation in NPC cells, and the present study confirms and extends this by showing that infection upregulates STIM1." (PMID 34684224, 2021). "By 48h post infection, the cells harbored very large inclusions that occupied most of the cytosol and still displayed large patches positive for STIM1 and CERT." (PMID 25915399, 2015). "As observed 4h post infection, CERT and STIM1 were mostly detected in puncta in close association with the bacteria." (PMID 25915399, 2015). "Ectopic HuR overexpression by infection with the AdHuR prevented the miR-195-mediated repression of Stim1 expression as indicated by an increase in the levels of Stim1 protein and mRNA in cells overexpressing miR-195." (PMID 23804758, 2013). "The pharmacological inhibition of STING during EV-D68 infection, using STING antagonist GSK′783, demonstrated that STING did not associate with PI4P but instead remained in the ER and associated with STIM1, confirming that EV-D68 interferes with STING canonical trafficking upon infection." (PMID 39459875, 2024). "In this study, we found vvIBDV infection increased the expression level of STIM1 and activated it." (PMID 35891504, 2022). "Our results showed that vvIBDV infection induced upregulation of endogenous STIM1 protein levels." (PMID 35891504, 2022). "Thus, we sought to study how vvIBDV infection modulated ER Ca2+ levels in a STIM1-dependent manner and identify the viral proteins that interact with STIM1." (PMID 35891504, 2022). "However, vvIBDV-infection led to redistribution and oligomerization of STIM1 in the cell membrane of infected cells." (PMID 35891504, 2022). "In our study, we found Ca2+ levels in the endoplasmic reticulum (ER) of vvIBDV-infected B cells were higher than that of mock-infected cells, and the expression level of stromal interaction molecule 1 (STIM1), an ER Ca2+ sensor, was significantly upregulated due to vvIBDV infection." (PMID 35891504, 2022). "Cell viability was not impaired by STIM1/2 deficiency 5 to 8 days after infection with recombinant lentiviruses expressing Cre recombinase in comparison to infected and non-infected Wt pmLF." (PMID 32321939, 2020).
infection (continued). "Finally, we attempted to inhibit bacterial protein synthesis during infection to address the role of potential C. trachomatis effector proteins in STIM1 recruitment to the inclusion." (PMID 25915399, 2015). "We discuss the potential role(s) of STIM1 during the infection process." (PMID 25915399, 2015). "These are involved in smooth-muscle function (FGFR1, GATA5 and STIM1), tissue organization (ADAMTS10), alveolar and epithelial function (ABCA3 and CLDN18), and inflammation and immune response to infection (CFH, CYTL1, HMCN1, LRBA and STIM1)." (PMID 36914875, 2023). "This siRNA was used to knock down STIM1 in DT40 cells, followed by infection with vvIBDV (MOI of 5)." (PMID 35891504, 2022). "By 14h post infection, the cells harbored multiple inclusions that displayed CERT and STIM1 positive-patches on their surface." (PMID 25915399, 2015). "STIM1 and CERT co-localization was more pronounced at that time and resembled the pattern observed 24h post infection, suggesting that the formation of ER-Inclusion MCSs was complete." (PMID 25915399, 2015). "To study whether vvIBDV infection activates STIM1 and CRAC channels, we performed Airyscan confocal microscopy assays to observe whether STIM1 shifts due to vvIBDV infection." (PMID 35891504, 2022). "Activated STIM1 interacted with Orai1 and activates CRAC channels, thereby increasing the Ca2+ level in the ER and promoting vvIBDV infection, which could be abolished by the inhibition of CRAC channels." (PMID 35891504, 2022). "In contrast, neither HuR protein levels nor Stim1 expression were altered by infection with the control adenovirus (Adnull)." (PMID 23804758, 2013). "The inclusions were still positive for CERT and STIM1 30h post infection (not shown)." (PMID 25915399, 2015).
cardiac diseases (8 papers, 2015 to 2024). "In addition, Stim1-Ser88Gly, a mutation recently discovered in a patient with heart disease (see discussion), is less robustly phosphorylated than Stim1-WT in vitro and in cells, suggesting that Fam20C phosphorylates Stim1-Ser88." (PMID 30520731, 2018). "Therefore, it is reasonable to speculate that STIM1 deficiency might lead to heart disease in humans." (PMID 29145451, 2017). "The previous studies have also identified additional miR-185 target genes, such as RhoA, Cdc42, and Stim1, that are pro-hypertrophic in the heart, suggesting further that miR-185 is a strong anti-hypertrophic miRNA in vivo and a potent therapeutic target for cardiac diseases." (PMID 25767890, 2015). "However, the STIM1-deficient patients had no clinical features of heart disease." (PMID 29145451, 2017).
neurodegenerative disease (7 papers, 2015 to 2024). A disorder of the central nervous system characterized by gradual and progressive loss of neural tissue and neurologic function. "This is a novel observation in sporadic AD that fits well with the proposal that STIM1 might be directly involved in the pathogenesis of neurodegenerative diseases." (PMID 30088035, 2018). "In addition, our research also suggests that STIM1 is a novel regulatory target for neutralizing microglial activation that may be advantageous in the prevention of progression of various neurodegenerative diseases or mental illness." (PMID 26732345, 2015).
adenocarcinoma (4 papers, 2013 to 2024). A common cancer characterized by the presence of malignant glandular cells. "Altogether, our results indicate that Lacticaseibacillus paracasei and Lactiplantibacillus plantarum postbiotics attenuate SOCE by reducing Orai1 and STIM1 expression in adenocarcinoma cell lines without having any significant effect on SOCE in normal colon mucosa cells." (PMID 38514909, 2024).
cardiovascular diseases (3 papers, 2012 to 2022). "While controversy remains as to the importance of SOCE in excitable cells, STIM1 and Orai1 are essential for cellular homeostasis and their disruption is linked to various diseases associated with aging such as cardiovascular disease and neurodegeneration." (PMID 35821821, 2022). "Collectively, these studies suggest that STIM1 has an important role in mediating cardiovascular disease although the regulatory mechanisms governing STIM1 expression and activity in the heart need to be further established." (PMID 35821821, 2022). "Given that it appears too much or too little cardiomyocyte STIM1 results in similar cardiovascular phenotypes, it is likely that STIM1 levels are tightly regulated and play significant roles in the precipitation of cardiovascular diseases." (PMID 35821821, 2022). "Another possibility is that SOCE mediated by STIM1 and Orai1 is involved in the pathophysiology of cardiovascular diseases." (PMID 22984609, 2012).
genetic disease (3 papers, 2022 to 2023). "Although STIM2 is commonly regarded as the primary regulator of basal Ca2+ entry, constitutive activation of STIM1 enhances background Ca2+ influx and, thereby, increases resting [Ca2+]i and/or ER Ca2+ levels in several genetic disorders." (PMID 36371290, 2022).
metabolic disease (3 papers, 2017 to 2026). A congenital disorder (due to inherited enzyme abnormality) or acquired (due to failure of a metabolically important organ) disorder resulting from an abnormal metabolic process. "Strikingly, we demonstrate that STIM1 gain-of-function improves cellular stress responses and glucose homeostasis in obese mice, underscoring the therapeutic potential of targeting Ca2+ homeostasis through STIM1 for metabolic disease treatment." (PMID 29243589, 2017). "Preliminary own findings indicate that mRNA levels of Stim1 are down-regulated in adipocytes isolated from obese and diabetic mice (El Hachmane and Olofsson, unpublished), thus suggesting that adipocyte SOCE may be disturbed also in mammalian metabolic disease." (PMID 29335300, 2018).
neurological diseases (3 papers, 2013 to 2024). "Because a continuing decline of STIM1 levels is observed in aged neurons, and also during neurodegeneration in sporadic AD patients as reported here, the loss of STIM1 could be taken into consideration to explain the pathogenesis of neurological diseases." (PMID 30088035, 2018). "Several previous studies have been done to investigate the potential involvement of SOCE mediated calcium metabolism in neurological disorders with focus on STIM1." (PMID 24358303, 2013). "Thus, this type of study of cell behaviour with decreased STIM1 levels is an experimental approach to understanding the role of Ca2+ signaling and Ca2+ homeostasis dysregulation in neurological diseases." (PMID 30088035, 2018).
psychiatric disorder (3 papers, 2015 to 2021). A disorder characterized by behavioral and/or psychological abnormalities, often accompanied by physical symptoms. "The locus most strongly associated with ADHD + DBDs on chromosome 11 is located in STIM1, a gene not previously implicated in ADHD, DBDs, aggression-related phenotypes, or psychiatric disorders." (PMID 33495439, 2021). "Further investigation of STIM1 function and SOCE in neurodevelopmental, neurodegenerative and psychiatric disorders could thus generate novel therapeutic insights." (PMID 29942250, 2018).
bacterial infections (1 paper, 2020). "Patients with CRAC channelopathy due to LOF mutations in ORAI1 and STIM1 suffer from life‐threatening viral and bacterial infections early in life." (PMID 32609955, 2020).
hematologic malignancies (1 paper, 2018). "Alterations of Orai1 and even more STIM1 in solid cancers have been exhaustively studied but, to our knowledge, no data are available concerning the expression of these proteins in hematologic malignancies." (PMID 30373149, 2018).
infectious disease (1 paper, 2022). A disorder directly resulting from the presence and activity of a microbial, viral, or parasitic agent in humans. "STIM1 and ORAI1 constitute the core machinery of the ubiquitous SOCE pathway and loss of function in these proteins is associated with severe immune and muscular disorders and infectious diseases." (PMID 36321903, 2022).
renal disease (1 paper, 2015). "There was attenuation of association of SNPs near RRM1|STIM1 and STON2|SEL1L after adjustment (although still significant at p<0.05, unadjusted for multiple comparisons), suggesting that these SNPs have effects on SCDA levels mediated through these clinical factors, in particular renal disease." (PMID 26540294, 2015).
STIM1 also shares sentences with these, for which no sentence is quoted: skeletal muscle disorder (7 papers); congenital myopathy (5); Kaposi's sarcoma (4); muscular disease (4); ichthyosis (3); Sjögren’s syndrome (3); Allergy (2); cardiac arrhythmias (2); colorectal tumor (2); dyslexia (2); esophageal squamous cell carcinoma (2); head and neck squamous cell carcinoma (2); hyposplenism (2); inflammation (2); lymph node metastasis (2); Miosis (2); multiple sclerosis (2); muscular atrophy (2); neck carcinoma (2); skin melanoma (2); stomach carcinoma (2); acquired immune deficiency syndrome (1); acute respiratory distress syndrome (1); alpha dystroglycanopathies (1); ampullary carcinoma (1); amyotrophic lateral sclerosis (1); asthenia (1); astrocytomas (1); atopic dermatitis (1); autoimmune hemolytic anemia (1).
A further 56 diseases each share a sentence with STIM1 in 1 paper.